RPS6KB2 (ribosomal protein S6 kinase B2)
Description:
Phosphorylates specifically ribosomal protein S6. Seems to act downstream of mTOR signaling in response to growth factors and nutrients to promote cell proliferation, cell growth and cell cycle progression in an alternative pathway regulated by MEAK7.
Synonyms: S6K2; SRK; p70-beta; STK14B; p70S6Kb; KLS; S6KB; S6Kbeta; S6Kβ; P70-beta-1; P70-beta-2; S6K-beta2; S6KI(2); p70(S6K)-beta
Tractability: Small molecule: a drug acting on it is in phase 1 trials; a high-quality ligand is known; it belongs to a druggable protein family. PROTAC: ubiquitination databases record sites on it; a small molecule that binds it is known.
Target class: Enzyme; Protein Kinase; AGC protein kinase p70 subfamily; Kinase; AGC protein kinase group; AGC protein kinase RSK family
Gene: Protein-coding gene on chromosome 11 (67,428,460 to 67,435,408, forward strand). Ensembl gene ENSG00000175634.
Subcellular location: Cytoplasm; Nucleus
Subcellular location (Human Protein Atlas): Cytosol
Pathways (Reactome):
Disease: Constitutive Signaling by AKT1 E17K in Cancer
Signal Transduction: AKT phosphorylates targets in the nucleus
Gene Ontology:
Molecular function: protein serine/threonine kinase activity; protein kinase activity; ATP binding; peptide binding; protein serine kinase activity; ribosomal protein S6 kinase activity
Biological process: positive regulation of translational initiation; TOR signaling; signal transduction; TORC1 signaling; translation
Cellular component: cytosol; nucleoplasm; cytoplasm; nucleus
Genetic constraint (gnomAD): Loss-of-function variants: 50 observed, 57.48 expected, observed/expected ratio (o/e) 0.87, 90% interval 0.69 to 1.1. The upper end of that interval is the gene's LOEUF score, 1.1, which puts it in group 4 of 6, group 1 being the genes least tolerant of losing a copy. Missense variants: 671 observed, 666.16 expected, observed/expected ratio (o/e) 1.01, 90% interval 0.94 to 1.07. Synonymous variants: 293 observed, 264.38 expected, observed/expected ratio (o/e) 1.11, 90% interval 1.01 to 1.22.
Homologues: Orthologues: chimpanzee RPS6KB2 (99% identical), macaque RPS6KB2 (98% identical), guinea pig RPS6KB2 (95% identical), mouse Rps6kb2 (93% identical), dog RPS6KB2 (89% identical), rat Rps6kb2 (86% identical), pig RPS6KB2 (85% identical), Drosophila melanogaster S6k (61% identical), Caenorhabditis elegans rsks-1 (53% identical), Caenorhabditis elegans R04A9.7 (36% identical), Drosophila melanogaster JIL-1 (35% identical), Caenorhabditis elegans rskn-2 (32% identical), and 1 more. Paralogues in human: RPS6KB1 (70% identical), RPS6KA3 (43% identical), RPS6KA2 (43% identical), RPS6KA1 (42% identical), RPS6KA6 (41% identical), RPS6KA5 (41% identical), RPS6KA4 (40% identical).
Diseases named in the same sentence as RPS6KB2 in open-access papers:
RPS6KB2 is named in the same sentence as 43 diseases in open-access papers, as found by Europe PMC text mining. Sharing a sentence is not in itself a finding about the gene and the disease. The quoted sentences say what the papers report.
breast carcinoma (15 papers, 2013 to 2024). "Previous studies revealed that both RPS6KB1 and RPS6KB2 exhibit amplifications or gene gains in breast cancer tissues." (PMID 35879299, 2022). "Amplification and expression of RPS6KB2 in breast cancer tissues are correlated with decreased tamoxifen responsiveness and poor prognosis in ER+/PR + tumors." (PMID 35608730, 2022). "These associations remained similar after additionally adjusted for breast cancer stage, despite that a more advanced stage was associated with relative over-expression of AKT1 and RPS6KB2, compared to an earlier stage." (PMID 35608730, 2022). "Studies in breast cancer tissues reported that RPS6KB2 gains/amplifications correlate with ER-positivity." (PMID 32054043, 2020). "A co-amplification of RPS6KB2 and 4EBP1 has been reported, suggesting a synergy between these mTOR targets in breast cancer development and progression." (PMID 32054043, 2020). "S6K2 encoded by the gene RPS6KB2 was shown to be located on chromosome 11q13, which harbors several key mediators of breast cancer." (PMID 32054043, 2020). "Breast cancer, head and neck cancer, cholangiocarcinoma, endometrial cancer, esophagogastric cancer, and ovarian and bladder cancer exhibited the highest alteration frequency, with amplification of RPS6KB2 being the most common copy number alteration." (PMID 39796034, 2024). "Along with RPS6KB2, high expression of EIF4EBP1 might be indicative of more aggressive breast tumor phenotypes as overexpression of EIF4EBP1 is associated with poor breast cancer prognosis." (PMID 35608730, 2022). "Differential expression of AKT1 and RPS6KB2 by race warrants further investigation to elucidate their roles in racial disparities of treatment resistance and outcomes between Black and White women with breast cancer." (PMID 35608730, 2022). "While amplification of RPS6KB2 is only associated with 4.3% of breast cancers, a large number of samples (21.3%) exhibit gains, suggesting that RPS6KB2 gain rather than amplification is a major event in breast cancer." (PMID 32054043, 2020). "However, we observed a relative under-expression of RPS6KB2 in breast cancer overall and in luminal tumors from Black women compared to White women, a finding that was opposite to our hypothesis." (PMID 35608730, 2022). "The normal development and the lack of an apparent phenotype in S6K2−/− mice suggests that it is a potential target in the treatment of endometrial, gastric and breast cancers, which have been shown to have RPS6KB2 amplification or elevated S6K2 expression." (PMID 32054043, 2020). "Thus, lower expression of TSC1, along with higher expression of RPS6KB2 and EIF4EBP1, can be indicative of more aggressive breast cancer phenotypes." (PMID 35608730, 2022). "Over-expression of RPS6KB2 and EIF4EBP1 and under-expression of TSC1 might be indicators of more aggressive breast cancer phenotypes." (PMID 35608730, 2022).
breast tumours (5 papers, 2013 to 2022). "In multivariable models, Black women had relative under-expression of AKT1 (log2 fold-change = − 0.31, 95% CI − 0.44, -0.18) and RPS6KB2 (log2 fold-change = − 0.11, 95% CI − 0.19, − 0.03) in their breast tumors compared to White women." (PMID 35608730, 2022). "In conclusion, AKT1 and RPS6KB2, two important prognostic predictors in the mTOR pathway, are expressed differently in breast tumors in Black and White women." (PMID 35608730, 2022).
melanoma (4 papers, 2020 to 2025). A malignant, usually aggressive tumor composed of atypical, neoplastic melanocytes. "Among these kinases, 6 (RPS6KB2, DSTYK, TBRG4, CDK4, POLR2E, FASTKD5) and 4 (STK26, PAK1, EPHB2 and JAK3) were consistently up- or down-regulated, respectively, in the metastatic lines of at least two pairs of melanoma cells." (PMID 32051510, 2020).
prostate carcinoma (4 papers, 2016 to 2024). A carcinoma that arises from epithelial cells of the prostate gland. "Therefore, RPS6KB2 is usually linked to cell proliferation and prognosis, such as in BC and prostate cancer." (PMID 37273920, 2023).
pulmonary fibrosis (3 papers, 2021 to 2023). Chronic progressive interstitial lung disorder characterized by the replacement of the lung tissue by connective tissue, leading to progressive dyspnea, respiratory failure, or right heart failure. "The rs1476792 SNP was also validated in ADs and is associated to RPS6KB2 (ribosomal protein), previously implicated in idiopathic pulmonary fibrosis and lung radiotoxicity via regulation of the mTOR signaling pathway and was dysregulated in World Trade Center responders with associated sarcoidosis." (PMID 38390497, 2023). "lncAP003419.16 is highly expressed in TGFβ1‐treated alveolar epithelial cells and IPF patients, in which lncAP003419.16 facilitates pulmonary fibrosis via the mammalian target of rapamycin (mTOR) signaling pathway dependent on its adjacent gene ribosomal protein S6 kinase B‐2 (RPS6KB2)." (PMID 33533071, 2021). "Compared with the control group, the BLM-induced pulmonary fibrosis group exhibited significantly higher expression of Fmod and Tgfbr2 mRNA; in contrast, the mRNA expression levels of Bambi, Skp1, Zfyve9, Zfyve16, Ppp2ca, Ppp2r1a, Ppp2r1b, Rps6kb1, and Rps6kb2 were markedly lower." (PMID 38259493, 2023).
glioblastoma (2 papers, 2012 to 2023). The most malignant astrocytic tumor (WHO grade IV). "NSUN6 controls glioblastoma response to temozolomide (TMZ) through NELFB and RPS6KB2 interaction." (PMID 37934565, 2023).
bladder cancers (1 paper, 2024). "A comparison of alteration frequencies between RPS6KB2 and RPS6KB1 in the TCGA pan-cancer dataset showed similar patterns, with amplification being the most common alteration across cancers, such as breast, endometrial, esophagogastric, ovarian, and bladder cancers." (PMID 39796034, 2024).
bovine tuberculosis (1 paper, 2019). "In addition, the gene RPS6KB2 was differentially expressed in Angus cattle selected for low and high residual feed intake and in bovine tuberculosis-infected and control cattle." (PMID 31665138, 2019).
cholangiocarcinoma (1 paper, 2024). A carcinoma that arises from the intrahepatic biliary tree (intrahepatic cholangiocarcinoma) or from the junction, or adjacent to the junction, of the right and left hepatic ducts (hilar cholangiocarcinoma). "The mRNA expression of RPS6KB2 across cancer subtypes generally mirrored its expression in normal tissues, except for cholangiocarcinoma, where significantly higher tumor-specific expression is evident." (PMID 39796034, 2024). "However, head and neck cancers and cholangiocarcinoma displayed a higher frequency of RPS6KB2 alterations compared to RPS6KB1." (PMID 39796034, 2024). "This pronounced expression of RPS6KB2 in cholangiocarcinoma may be attributed to differences in transcriptional regulation, unique subcellular localization, or interactions with specific protein complexes, suggesting its distinct oncogenic functions in this cancer subtype." (PMID 39796034, 2024).
emphysema (1 paper, 2021). "The cytosolic transport (RNF126, PLEKHJ1, VPS51, and AP1G1), target of rapamycin (mTOR) signaling (PIK3CA, STK11, RPS6KB2, and PRR5), regulation of translation, metabolic regulation, and apoptosis are involved in the percent emphysema-associated network." (PMID 34777474, 2021).
esophagitis (1 paper, 2016). An acute or chronic inflammatory disease affecting the esophageal wall. "In our analysis, we found that RPS6KB2:rs10274 was the most significant SNP associated with the risk of esophagitis." (PMID 26991123, 2016). "After multiple comparisons, RPS6KB2 and SMO binding site SNPs remained significantly associated with radiotherapy-induced acute esophagitis, while TNFRSF10D:rs7957 was significantly associated with radiotherapy-induced acute pneumonitis." (PMID 26991123, 2016). "After multiple comparison corrections, three SNPs (RPS6KB2:rs10274, SMO:rs1061280, SMO:rs1061285) remained significantly associated with esophagitis (q<0.1)." (PMID 26991123, 2016). "After multiple comparison correction, RPS6KB2:rs10274, SMO:rs1061280, SMO:rs1061285 remained significantly associated with esophagitis, while processing gene DGCR8:rs720014, DGCR8:rs3757, DGCR8:rs1633445 remained significantly associated with pneumonitis." (PMID 26991123, 2016). "eQTL analysis showed that the top SNP (RPS6KB2:rs10274) for esophagitis analysis could potentially affect RPS6KB2 expression." (PMID 26991123, 2016).
gastric carcinoma (1 paper, 2023). A carcinoma that arises from epithelial cells of the stomach. "RPS6KB2 is also highly expressed in about 5% of patients with gastric carcinoma; this high expression is associated with decreased overall survival rates of patients with the late-stage disease." (PMID 37273920, 2023).
Insulin resistance (1 paper, 2020). Increased resistance towards insulin, that is, diminished effectiveness of insulin in reducing blood glucose levels. "The samples from the carotid sheath showed an enriched expression of genes described to play a role in insulin resistance (PPP1R3E, PRKCQ, PRKCZ, CPT1B, MGEA5, RPS6KB2, OGT; KEGG_PATHWAY hsa04931:Insulin resistance)." (PMID 32661330, 2020).
lung adenocarcinoma (1 paper, 2020). A carcinoma that arises from the lung and is characterized by the presence of malignant glandular epithelial cells. "Indeed, an analysis of TCGA data using cBioPortal reveals that RPS6KB1 and RPS6KB2, the two isoforms of P70S6K, are amplified or over-expressed in 20% and 11% of lung adenocarcinoma cases, respectively." (PMID 32513387, 2020).
lymphoma (1 paper, 2023). A malignant (clonal) proliferation of B- lymphocytes or T- lymphocytes which involves the lymph nodes, bone marrow and/or extranodal sites.
cancer (22 papers, 2009 to 2024). A tumor composed of atypical neoplastic, often pleomorphic cells that invade other tissues. "Next, to investigate the relevance of targeting S6K2 in different types of cancer, we checked the expression levels and the copy number alterations of RPS6KB2, the gene encoding S6K2, using the GEPIA and cBioPortal interfaces on the TCGA and GTEx databases." (PMID 39796034, 2024). "In the 8p12/11q13 coamplified regions, EIF4EBP1 and RPS6KB2 could be co-targeted and play a synergistic role associated with the development and cancer progression as AKT/MTOR activators." (PMID 24416132, 2014). "The cBioPortal interface was used to analyze the alteration frequency of the RPS6KB2 gene in different cancers based on the TCGA pan-cancer dataset." (PMID 39796034, 2024). "High RPS6KB2 expression is correlated with chemotherapy resistance and prognosis of BC patients, indicating its potential role in cancer treatment." (PMID 37273920, 2023). "The silencing of the RPS6KB2 gene provided some insight into its function in regulating malignant cell proliferation and suggested a potential role in cancer therapy." (PMID 34680283, 2021). "RPS6KB2, the target gene of miR-4433a-3p, participates in cancer progression through the mTOR signalling pathway." (PMID 30381359, 2018). "RPS6, 70 kDa, polypeptide 2 (RPS6KB2) and PTEN were strongly associated with the activation of the mTOR signaling pathway in cancer, while mTOR pathway activation demonstrated higher expression of RPS6K, S6, 4E-BP1 and eIF-4G, linked with more aggressive clinical behavior." (PMID 26275051, 2015). "For example, miR-146b-3p and miR-4433a-3p could, respectively, target NOS2 (nitric oxide synthase 2) and RPS6KB2 (ribosomal protein S6 kinase B2) of the HIF-1 signalling pathway and the mTOR signalling pathway, leading to the proliferation and invasion of cancers." (PMID 30381359, 2018).
tumor (17 papers, 2013 to 2024). "For RPS6KB2, gene expression seemed to indicate more aggressive tumor characteristics." (PMID 35608730, 2022). "High vs. low tumor grade had relative over-expression of EIF4EBP1 (log2 fold-change = 0.84, 95% CI 0.46, 1.22) and RPS6KB2 (log2 fold-change = 0.33, 95% CI 0.15, 0.50), but under-expression of TSC1 (log2 fold-change = − 0.23, 95% CI − 0.38, − 0.08)." (PMID 35608730, 2022). "This crosstalk from MAPKs to β-catenin appears to be mediated through the phosphorylation of GSK3β and potentially by the ERK-mediated activation of the ribosomal proteins p70 S6 (officially known as RPS6KB2) and p90 RSK (officially known as RPS6KA1), as described in a variety of tumour cells." (PMID 24816560, 2014).
RPS6KB2 also shares sentences with these, for which no sentence is quoted: lung carcinoma (7 papers); non-small cell lung carcinoma (6); cardiac hypertrophy (5); brain tumors (2); endometrial cancer (2); small cell lung carcinoma (2); anaplastic oligoastrocytoma (1); cholera (1); CNS tumours (1); colorectal cancer (1); diabetes (1); head and neck cancer (1); idiopathic pulmonary fibrosis (1); infection (1); leiomyoma (1); lymph node metastasis (1); medulloblastoma (1); myopathy (1); osteosarcoma (1); pneumonitis (1); rectal carcinoma (1); sarcoidosis (1); schizophrenia (1); tauopathies (1); tendinopathy (1); virus infection (1).